KEAP1 (kelch like ECH associated protein 1)
Diseases named in the same sentence as KEAP1 in open-access papers (continued):
Sharing a sentence is not in itself a finding about the gene and the disease.
cancer (continued). "Our data expand on the causes of T-cell suppression as we have further identified an increase in immunosuppressive markers expressed on KEAP1-mutant cancer cells that inhibit the T-cell response (PD-L1, CD80/CD86, and CD155)." (PMID 38542481, 2024). "We summarized the literature on Keap1-Nrf2 signaling pathway and summarized the following three aspects: structure, function pathway, and cancer and clinical application status." (PMID 38634043, 2024). "Taken together, KEAP1 KO significantly promotes an immunosuppressive cancer cell phenotype through alterations of the secretome, regulation of surface markers, and gene expression changes consistent with modified regulation of immune trafficking." (PMID 38542481, 2024). "Given the high mutation frequency of KEAP1 in NSCLC, our focus was primarily on this cancer type to identify specific indications for AURKA inhibitors." (PMID 38521813, 2024). "The various functions of Nrf2 in the progression of cancer were investigated utilizing Keap1 knockdown mice in a 2016 study." (PMID 39286246, 2024). "Typically, p62 is overexpressed in BCa and promotes tumor growth through Keap1-Nrf2 signaling and protecting cancer cells from OS." (PMID 37810967, 2023). "For instance, functional studies in mice show that Nrf2 activation in hepatocytes resulting from specific KEAP1 deletion protects against fibrosis and cancer." (PMID 37627562, 2023). "Nuclear Factor Erythroid 2-Related Factor 2 (NFE2L2 or NRF2)/Kelch Like ECH Associated Protein 1 (KEAP1) signalling is one of the most important pathways involved in chemoresistance onset and cancer progression." (PMID 37175546, 2023). "A comprehensive genomic analysis of squamous cell lung cancers revealed that 34% of these cancers harboured somatic mutations in NFE2L2 (19%), KEAP1 (12%) or CUL3 (7%), resulting in the downregulation of NRF2 repressors and activation of NRF2." (PMID 37047696, 2023). "CDDO-Me is more potent than CDDO in terms of its anticancer and cancer-preventive activities and ability to activate the Keap1/Nrf2/ARE pathway, which is involved in cytoprotection in the presence of excessive electrophiles or oxidative stress." (PMID 37950261, 2023). "The inactivation of genes involved in protein degradation such as tumor suppressor genes KEAP1 and FBXW7 has been previously implicated in sensitivity and resistance to cancer immunotherapy, respectively." (PMID 36669486, 2023). "The findings of this study indicated that the treatment of SKOV3 cancer cells with ALT increased KEAP1 mRNA and protein levels, but Nrf2 protein level was decreased." (PMID 37712005, 2023). "Mutations in STK11, CDKN2B, KEAP1, CTNNB1, MET, and KRAS were associated with a significantly increased risk of cancer-associated thrombosis." (PMID 38069251, 2023). "The most abundantly studied are MAPK pathway inhibitors, and the common mechanisms of resistance are the reactivation of MAPK pathways such as DUSP7, NF2, and the KEAP1/Nrf2 pathway, which are present in multiple cancer resistance models." (PMID 38084101, 2023). "This is caused by alternative carcinogenic pathways induced by the genomic heterogeneity in these cancers, such as PD-L1 expression or co-mutations in STK11 and KEAP1." (PMID 37110848, 2023). "As an important regulator of oxidative stress, the Nrf2/Keap1 pathway also plays an important role in aging and various diseases, including preeclampsia, traumatic brain injury, and cancer." (PMID 37686132, 2023). "Given that KEAP1 and NRF2 are frequently mutated in cancer, it will be interesting to explore the involvement of TFEB/TFE3 in NRF2-driven cancers." (PMID 37216554, 2023). "As indicated in this study, KEAP1 was differently expressed in tumors and related to the prognosis of certain types of cancers." (PMID 37251921, 2023).
cancer (continued). "Our results build on these previous findings and further underscore the poor prognosis and high unmet medical need that exists in patients with aNSCLC with co-occurring mutations in STK11 and KEAP1, with either KRAS WT cancer or KRAS G12C–positive cancer." (PMID 37069542, 2023). "Numerous mutations (such as insertions and nonsynonymous substitutions) characterize the coding region of the Keap1 gene in cancer cells and have been identified in liver, gallbladder, and lung cancer cells." (PMID 37109574, 2023). "The activity that we have described recognizes the potential benefit of inhibiting the SUMOylation of KEAP1 as a cancer therapy." (PMID 37660919, 2023). "Meanwhile, this polysaccharide implied anti-cancer action against ID-8 cells bearing-mice through up-regulation of mRNA and protein expressions of Keap1, Nrf2 and HO-1 in liver and kidney tissues." (PMID 36875839, 2023). "Activating mutations of NFE2L2 and inactivating mutations of KEAP1 are found in approximately 6% and 4% of HCC, and confer to cancer cells an advantage of resistance to oxidative stress through the inhibition of KEAP1-mediated degradation of NRF2." (PMID 36765775, 2023). "We categorized patients with KRAS G12C, KEAP1, and STK11 mutational status using both solid and liquid assays; patients with cancer that was categorized as WT were assigned based on solid assays only." (PMID 37069542, 2023). "The Nrf2/Keap1 pathway plays a key role in maintaining cellular homeostasis and has anti-cancer properties." (PMID 37841775, 2023). "This significant difference was also observed in the other cancer cohorts, implying that KEAP1 regulates NRF2 activity in various cancers." (PMID 37633973, 2023). "Genomic profiles of cancer patients identified that tumor-induced mutations in KRAS, STK11, KEAP1, CDKN2B, CTNNB1, and MET are significantly associated with cancer-associated thrombosis." (PMID 37046748, 2023). "Due to its ability to impede apoptosis and hence stimulate tumor cell proliferation, invasion, and chemoresistance, the NRF2/KEAP1 pathway is also essential in the development of cancer." (PMID 37927596, 2023). "This suggests that PRMT5 binding to R596 on Keap1 inhibits ubiquitination and degradation of Keap1, thereby down-regulating Nrf2 and expression of its downstream gene and promoting the innate resistance of cancer tissues to immunotherapy." (PMID 38259518, 2023). "As Nrf2 inactivation contributes to the development of chronic diseases and cancer initiation, interfering with the protein binding to its negative regulator Keap1 directly or indirectly is a possible strategy for therapy." (PMID 37109574, 2023). "The Nrf2/KEAP1 signalling pathway is also reported to play a critical role in the response of several cancer types to chemotherapy." (PMID 37371607, 2023). "polysaccharide possessed anti-cancer activity on HepG2 cells involved with reduction of Nrf2 protein expression, and enhancement of protein expression of Keap1, HO-1, NQO1, GST1, SOD2, GPX, and GCLM." (PMID 36875839, 2023). "Inactivation of Keap1 strongly induces Nrf2, and this phenomenon is often observed in cancer cells, enabling them to acquire malignancy by perverting Nrf2 activity." (PMID 37416770, 2023). "Among them, 6 co-opted E3 ligases, such as MDM2 and KEAP1, were highly expressed in over 30 cancer types, suggesting their high potential for broad usage in multiple cancer types." (PMID 37845222, 2023). "The cysteine-rich structure of Keap1 can be considered as a measure of the oxidative status of the cell, highlighting the importance of a correct regulation of the Keap1-Nrf2 axis in cancer formation." (PMID 36771023, 2023). "The overexpression of Nrf2 due to Nrf2 machinery mutations (e.g., somatic mutations in Keap1, Nrf2, or Cul3; epigenetic DNA methylation of Keap1; etc.)or Nrf2/Keap1 post-translational modifications, promote cancer development and resistance." (PMID 36771023, 2023).
cancer (continued). "A decrease in Keap1 expression unlocks Nrf2 transcriptional activity, which increases the expression of proteins that contribute to the survival and proliferation of cancer cells." (PMID 37109574, 2023). "These recurrent KEAP1 and NRF2 mutations (and in addition, missense mutations in Cul3) lead to metabolic reprogramming and allow cytoprotective action to cancer cells resulting in enormous proliferation and resistance to anticancer therapy." (PMID 37375797, 2023). "NRF2 activation in cancer cells is closely related to multiple pathways, such as NRF2 gene mutation leading to overactivation of NRF2 in cancer cells; P62 accumulation competes with NRF2 to bind Keap1 to that NRF2 accumulates in tumor cells." (PMID 36697441, 2023). "In this article, we reviewed the structure and function of the Nrf2/Keap1 system and the development of natural Nrf2 inhibitors with an emphasis on their biological function on cancer." (PMID 37416770, 2023). "The Keap1/Nrf2 pathway acts as a double-edged sword in cancer cells, and previous studies have demonstrated the involvement of this pathway in various cancers, including gallbladder and pancreatic cancer." (PMID 38247453, 2023). "As mentioned, activation of Nrf2/Keap1 signaling in cancer cells results in chemoresistance, inactivating drug-mediated oxidative stress and protecting cancer cells from drug-induced cell death." (PMID 36978983, 2023). "Abnormal activation of KEAP1/NRF2 can prevent cancer cells from being harmed by oxidative stress and improve the survival chance of cancer cells." (PMID 35911967, 2022). "An alternative pathway for NRF2 degradation, which is instead KEAP1-independent, has been also identified in mouse cells and human cancer cells, and it is intimately connected with PI3K/AKT signaling." (PMID 35954245, 2022). "Gain-of-function mutations in NFE2L2, loss-of-function mutations in key members of the KEAP1/CUL3/RBX1 E3-ubiquitin ligase complex, and succination of KEAP1 have proven to activate the NRF2 pathway in many cancer types." (PMID 36068196, 2022). "In the end, the role of miRNAs which target NRF2/KEAP1 axis in cancer cells is most likely dependent on the broader cellular context." (PMID 35268568, 2022). "The following paragraph aims to outline the mechanism of NRF2/KEAP1 epigenetic modifications in cancer." (PMID 35754474, 2022). "Restoring Keap1 expression promoted the in vitro migration and invasion of cancer cells, whereas Keap1α expression alone had the opposite effects." (PMID 36142252, 2022). "For instance, STK11 (20.59% v 5.95%, odds ratio [OR] = 4.10), KEAP1 (15.38% v 4.61%, OR = 3.76), and MUTYH (4.96% v 2.35%, OR = 2.17) were more frequently mutated in KRASG12C-mutant tumors across all cancer types (P < .001 and FDR-P < .01 for all comparisons)." (PMID 35319967, 2022). "In this study, the TCGA database data mining identified that KEAP1 is up-regulated in most cancer types." (PMID 35453346, 2022). "The Keap1/Nrf2/HO-1 signalling pathway is recognised as an important antioxidant system that protects cancer cells from ferroptosis." (PMID 35350242, 2022). "Cancer cell proliferation leads to the accumulation of Reactive Oxygen Species (ROS) which activate the Keap1-Nrf2 signaling pathway." (PMID 36203462, 2022). "The P62, when expressed in cancer cells, blocks the degradation of Nrf2 and increases its stimulation, translocation, or nucleation by inactivating Keap1, resulting in the prevention of ferroptosis in the cancer cells." (PMID 35408533, 2022). "Keap1 is an essential regulator of Nrf2 functions, and the role of Keap1 in regulating Nrf2 signaling in cancers has been reported previously." (PMID 35945195, 2022).
cancer (continued). "Persistent activation of Nrf2 signaling has been detected in many different human cancers and is frequently the result of somatic mutations of the NRF2/KEAP1 genes." (PMID 36289675, 2022). "On the other hand, lncRNA MALAT-1 was observed to be overexpressed in different cancer cell lines and to lower KEAP1 activity." (PMID 36077530, 2022). "Across cancer types with KEAP1 alterations, TMB is significantly higher (10 vs. 4 muts/Mb, p < 0.0001) and OS is significantly shorter (39 vs. 109 months, p < 0.0001))." (PMID 36136862, 2022). "We evaluated the clinicopathological correlates of the 7 SMGs, together with 6 additional cancer genes identified from at least 2 previous HCC genomics studies and mutated in ≥3 HCCs of the current cohort (APOB, ARID2, CDKN2A, KEAP1, RB1 and TSC2)." (PMID 35508466, 2022). "Herein, our evidence has also been provided that deletion of Keap1 inhibited the in vitro migration and invasion of cancer cells, whereas Keap1β expression alone showed the opposite results." (PMID 36142252, 2022). "Analyses of Cancer Cell Line Encyclopedia data also revealed that KEAP1 mutant NSCLC cells generally exhibit higher expression of FSP1 than do KEAP1 WT ones." (PMID 35459868, 2022). "A great deal of previous research into the NRF2/KEAP1 signaling focuses on the dual roles of NRF2 in cancer." (PMID 35754474, 2022). "KEAP1 alterations were seen in ~3% across 40,000 distinct cancer types in a pan-cancer study, with the highest prevalence seen in NSCLC (15.8%)." (PMID 36136862, 2022). "Intriguingly, it has been reported that epigenetic mechanisms profoundly influence oxidative stress responses through NRF2/KEAP1 signaling and further play an essential role in cancer." (PMID 35754474, 2022). "In proteins homologous to PfK13 such as the KEAP1 protein, whose dysfunction is involved in certain cancers, the BTB domain mediates varying oligomerization architectures and interacts with the cullin-3 ubiquitin ligase." (PMID 34606334, 2022). "The prognostic value of KEAP1 alterations was found in early-stage (p = 0.0099) and associated with markedly inferior DFS in early-stage cancers (p = 0.0009)." (PMID 36136862, 2022). "In this work, we investigated how some of the DPP III mutations listed in the cBioPortal cancer genome database affect enzyme activity, the affinity of DPP III for the Kelch domain of the KEAP1 protein, and the KEAP1-NRF2 pathway." (PMID 35216111, 2022). "The mRNA level of KEAP1 was significantly positively correlated with the changes in somatic copy number in most cancer types examined except DLBC, KICH, and THYM." (PMID 35453346, 2022). "Activation of Nrf2 is a frequent event in cancer and can be caused by somatic mutations in the NRF2 gene as well as in the KEAP1 gene." (PMID 36581625, 2022). "The Keap1 protein is the master modulator of Nrf2 pathway; moreover, it is the hub of such important processes as cancer, cell stress, inflammation, and chemio- and radio-resistance." (PMID 35362892, 2022). "Among these Nrf2 modulators, there are natural compounds that target and significantly inhibit the Keap1-Nrf2 pathway, most of which are safe (including dietary phytochemicals) and have shown promise against chemoresistant cancer cells." (PMID 36552553, 2022). "KEAP1 loss-of-function mutations occur in various cancer types and can decrease NRF2 degradation to activate the KEAP1/NRF2 antioxidant response pathway, which confers a poor prognosis." (PMID 35813464, 2022). "In fact, the Keap1–Nrf2 antioxidant system, which comprises also Dpp3 among its activators, is known to exert both protective and detrimental effects, in cancer as well as in bone biology, acting both on the osteoclast and on the osteoblast lineage." (PMID 35745051, 2022). "Multiple studies have indicated that epigenetic alterations in the Keap1 gene donate a growth advantage to cancer cells and are correlated with poor clinical prognosis in cancer patients." (PMID 35773670, 2022).
cancer (continued). "In Group A, 382 DEGs regulated in Keap1−/− cells were generally involved in signal transduction, cancer, infectious disease, transport and catabolism, metabolic processes, and cellular processes." (PMID 36142252, 2022). "TRIM15 directly targeted Keap1 by ubiquitination and degradation, promoting Nrf2 stabilization, and ultimately an increased proliferation and invasion of cancer cells." (PMID 35534896, 2022). "In the tumour-bearing tissue formed by Keap1−/− cells, the overall colouration of the cells was darker, and there were a large number of cancer grooves in the formed tumours to wrap the tumour cells." (PMID 36142252, 2022). "Here, we present current advances in respect to the role of NRF2/KEAP1 signaling in cancer oxidative stress, with a particular emphasis on how this pathway can be regulated by epigenetic mechanisms to affect cancer initiation and progression." (PMID 35754474, 2022). "Both KEAP1 and NRF2 are considered as cancer drivers in multiple cancer types, however, most of the mutations found are still lacking experimental conformation." (PMID 35216111, 2022). "In Group C, 122 DEGs regulated in Keap1-Restored cells were significantly enriched in the cellular community, endocrine system, cancer, signal transduction, immune system process, localization, and developmental process." (PMID 36142252, 2022). "In Group M, 710 DEGs regulated in Keap1-Restored cells were generally involved in signal transduction, immune system, cancer, immune system process, biological adhesion, metabolic process, and developmental process." (PMID 36142252, 2022). "The Nrf2/Keap1/p62 antioxidant system has been shown to play important roles in a variety of diseases, including neurodegenerative diseases and cancer, making it an attractive therapeutic target for the treatment of these diseases." (PMID 34838592, 2022). "As a consequence, the restoration of Keap1α enabled a significant tumour-preventing effect on subcutaneous human carcinoma xenografts in nude mice, but the recovery of Keap1 promoted the tumour effect." (PMID 36142252, 2022). "The results obtained were as follows: the human carcinoma derived from Keap1−/− tumours were estimated to be only three-times smaller than those derived from Keap1-Restored cells, but four-times larger than those derived from Keap1α-Restored cells." (PMID 36142252, 2022). "The resulting images showed that the carcinomas derived from Keap1+/+ cells were estimated to be seven-times in tumour volume and weight larger than those of Keap1−/− cells and also three-times than that of Keap1β(Keap1Δ1–31) cells." (PMID 36142252, 2022). "KLHL members associated with inherited forms of the human disease include KLHL3, KLHL7, KLHL9, KLHL12, and GAN (KLHL16), whereas KLHL6, KEAP1 (KLHL19), KLHL20, and ENC1 (KLHL37) are associated with cancer." (PMID 33897412, 2021). "But until now little success has been achieved in developing safe and effective KEAP1/NFE2L2 inhibitors for cancer therapy." (PMID 34381706, 2021). "Many Nrf2 or Keap1 inhibitors have been reported as potential anticancer agents for different cancers." (PMID 33841137, 2021). "This apparently contradictory effect of the NRF2/KEAP1 signaling pathway in cancer (cell protection against cancer versus pro-tumoral properties) has generated a great controversy about its functions in this disease." (PMID 34440648, 2021). "A somatic mutation in highly conserved Kelch or the intervening region domain of the Keap1 protein that results in the constitutive activation of Nrf2 often occurs in cancer cells." (PMID 33895141, 2021). "Specifically, we found that blades I, II and III in the Kelch β-propeller structure appear to be the least stable, which, taken together with their observed mutational frequency, points to stability as a possible target of cancer in the Kelch domain of KEAP1." (PMID 34065616, 2021). "Given the importance of the NRF2-KEAP1 system in cancer, we evaluated the effect of KEAP1 on NRF2 DLG MTs in HCC." (PMID 34069882, 2021).